VDR (vitamin D receptor)
Diseases named in the same sentence as VDR in open-access papers (continued):
Sharing a sentence is not in itself a finding about the gene and the disease.
melanoma (continued). "This review discusses the role of vitamin D in melanoma and how CYP-mediated metabolism can potentially affect the actions of vitamin D. Through interacting with the retinoid X receptor, VDR signaling leads to anti-inflammatory, antioxidative, and anticancer actions." (PMID 38672780, 2024). "Similarly to VDR, CYP27B1 expression was also lower in highly pigmented melanomas than in amelanotic or slightly pigmented melanomas." (PMID 38927967, 2024). "Importantly, we also noticed the upregulation of the VDR and a slight downregulation of CYP24A1 protein level in melanoma cells simultaneously treated with 1,25(OH)2D3 and CPL304110 compared to monotreatment with the novel FGFRs inhibitor." (PMID 38473753, 2024). "Cytoplasmic immunolocalization of VDR was also lower in melanomas that developed metastases than in non-metastasizing melanomas." (PMID 38927967, 2024). "The presence of VDR expression and the lack of ulceration delineated better overall survival than melanomas without VDR expression and with or without ulceration." (PMID 38927967, 2024). "In addition, the vitamin D receptor (VDR) and retinoic acid orphan receptors (ROR)α and γ expression decreased in melanized melanoma cells in comparison to amelanotic or poorly pigmented cells." (PMID 35359389, 2022). "Additionally, an inverse correlation has also been documented between the expression of the vitamin D receptor (VDR) and a crucial vitamin D activating enzyme (CYP27B1) with melanoma progression and disease outcome." (PMID 35004285, 2021). "However, we observed a significant increase in VDR protein level in RPMI-7951 and SK-MEL-28 melanoma cells treated with 1,25(OH)2D3." (PMID 35004285, 2021). "Less advanced melanomas, like those with fewer than three lymph node metastases and those without distant metastases, had the strongest VDR expression." (PMID 34692525, 2021). "This is consistent with clinicopathological studies showing an inverse correlation between melanoma progression and VDR expression, with very poor disease outcome in VDR negative melanomas." (PMID 34206371, 2021). "Finally, an inverse correlation between vitamin D receptor, VDR, and 1α-hydroxylase (CYP27B1), the enzyme responsible for the synthesis of the biologically active form of vitamin D, was documented with melanoma progression and disease outcome." (PMID 35004285, 2021). "Significant effects of 20(OH)D3 and 1,20(OH)2D3 on the WM164 melanoma cells lacking VDR expression, shown in this study, support recent findings that other receptors besides the VDR mediate some of the effects of vitamin D derivatives." (PMID 34206371, 2021). "Next, we checked whether the preincubation of A375 melanoma cells with vitamin D derivatives affected the protein level of VEGFR1, VEGFR2, PDGFRa, PDGFRb, or VDR after subsequent treatment with cediranib." (PMID 35004285, 2021). "Malignant melanomas that retained exclusive nuclear VDR at the tumor base did not metastasize in this study." (PMID 32572587, 2020). "VDR expression has been shown to be lower in pigmented melanoma cells compared with nonpigmented cells." (PMID 32429485, 2020). "Furthermore, the expression of vitamin D3-related genes was altered by vitamin D3 analogs, and the effects on the expression of VDR, RXR, PDIA3, CYP2R1 or CYP24A1 were stronger in WM98 melanoma cells in comparison to the A375 line." (PMID 30200275, 2018). "The antiproliferative activities of 21(OH)pD appear not to require VDR translocation to the nucleus, which explains the high efficacy of this noncalcemic pregnacalciferol analog in SK-MEL-188b melanoma, that is, VDR−/−." (PMID 30200275, 2018). "Recently, important biological mechanisms have been examined for their contribution to the development and progression of malignant melanoma, including the phosphatidylinositol 3-kinase (PI3K)/PTEN/AKT/mTOR signaling pathway and the nuclear vitamin D receptor (VDR) function." (PMID 29100280, 2017).
melanoma (continued). "Current studies on rodent melanomas show that expression of VDR is below the level of detectability in non-pigmented cells by conventional PCR." (PMID 25811927, 2015). "The higher expression of CYP24A1 in strongly pigmented melanomas was a rather unexpected finding since our previous studies have shown a negative correlation between VDR and CYP27B1 expression." (PMID 25334067, 2014). "The lack of VDR in primary melanomas was related to worse overall survival of melanoma patients." (PMID 38927967, 2024). "Two human malignant melanoma cell lines, A375 and SK-MEL-28, were selected to analyze the effects of these hydroxy-derivatives on cell proliferation and migration, cell cycle modulation, changes in the expression of selected genes and VDR translocation to the nucleus." (PMID 39456696, 2024). "The anti-melanoma effects of 20,24(OH)2D3, which, unlike the other two secosteroids, tested lacks a 1α-hydroxyl group, was relatively weak, confirming the requirement for a 1α-hydroxyl group for strong interaction with the VDR." (PMID 39456696, 2024). "Furthermore, the short side-chain analog 21(OH)pD was found to be superior among vitamin D analogs and was the only one, which inhibited the growth of the melanoma subline negative for VDR, indicating a mechanism of action that is VDR-independent." (PMID 30200275, 2018). "Furthermore, incubation of human malignant melanoma SK-MEL 188b cells with active form of vitamin D3 did not lead to the appearance mRNAs for either VDR or CYP24A1." (PMID 26760999, 2016). "The lack of stimulation of CYP24A1 expression in murine B16-F10 melanoma cells by 21(OH)pD may be explained by the impaired interaction with the VDR." (PMID 25811927, 2015). "Furthermore, pigmented B16 melanoma cells show attenuation of responsiveness to ligand stimulation of VDR translocation to nucleus, and expression of VDR and CYP24A1 genes, indicating that VDR signaling is malfunctioning in melanotic cells." (PMID 25811927, 2015). "Moreover, 1,25(OH)2D3 has been shown to suppress the growth of human malignant melanoma (MM)-derived xenografts (expressing the VDR) in immunosuppressed mice, but not in a VDR-negative MM cell line." (PMID 22276021, 2009). "Due to the notable reduction in VDR and CYP27B1 expression, researchers believe that the low levels of these proteins promote melanoma development because of the lack of antiproliferative action of vitamin D." (PMID 38672780, 2024). "All our analogues induced differentiation of the VDR positive A375 and VDR negative SK-MEL 188b human malignant melanoma cell lines." (PMID 30037036, 2018). "PCR fragments characteristic for VDR, CYP27A1 and CYP27B1 mRNAs were below the level of detectability in SK-MEL-188b melanoma, which did not respond to vitamin D. Only the mRNA of PDIA3 was detected in this line." (PMID 30200275, 2018). "A series of double point modified (DPM) analogs of 1,25-dihydroxyvitamin D2 (1,25(OH)2D2) induced differentiation of the vitamin D receptor (VDR) positive A375 and VDR negative SK-MEL 188b human malignant melanoma cell lines." (PMID 26760999, 2016). "Administration of 1 μM 1,25(OH)2D3 to B16-F10 cells increased VDR and CYP24A1 mRNA levels in both pigmented and non-pigmented melanoma cells." (PMID 25811927, 2015).
rickets (100 papers, 2007 to 2026). Bone softening and weakening usually caused by deficiency or impaired metabolism of vitamin D. Deficiency of calcium, magnesium, or phosphorus may also cause rickets. "The GG genotype of rs10877012 CYP27B1 was significantly associated with susceptibility of having hypovitaminosis D, whereas the CT genotypes of rs731236 TaqI VDR confer susceptibility to RA and high clinical disease activity in the Mexican mestizo population." (PMID 40870018, 2025). "Pathological fractures, secondary hypoparathyroidism, and vitamin D-resistant rickets are linked to the single-nucleotide BsmI polymorphism (VDR rs1544410), which affects osteogenesis and vitamin D sensitivity." (PMID 40629773, 2025). "In mice, VDR gene ablation elicits both rickets and hair loss, while point mutations specifically compromising either 1,25(OH)2D ligand or coactivator contacts in human VDR result in rickets without hair cycle disruption." (PMID 38676447, 2024). "The first discovery of a missense mutation in the VDR gene was reported first in 1991 in Japanese rickets patients from heterozygous carrier parents." (PMID 38318147, 2024). "Depending on the location of the mutations in the VDR gene, individuals with VDR mutation-induced rickets can be sub-grouped as having defects in hormone and DNA binding activity on VDR or restrains that prevent VDR nuclear localization." (PMID 38318147, 2024). "There are several VDR polymorphisms implicated in nutritional rickets, with the most studied polymorphisms occurring in intron 8 (Bsm I (b alle) and Apa I sites), exon 9 (Taq I site), the 3′untranslated region (3’UTR), and exon 2 (Fok1 site)." (PMID 36619587, 2022). "VDR gene mutation leading to hypocalcemia, secondary hyperparathyroidism, and severe early age rickets." (PMID 36246903, 2022). "This review has identified a trend correlating hypovitaminosis D and the expression of certain VDR genotypes, which can indicate the risk for malignant progression in patients with OPMDs due to alterations in immune response." (PMID 35218642, 2022). "As the binding affinity of 1,25(OH)2D3 for VDR is much higher than that of 25(OH)D3, impaired transcriptional activity of 1,25(OH)2D3 causes typical bone disorders such as osteomalacia and rickets associated with hypocalcemia." (PMID 35869242, 2022). "Several studies have associated VDR polymorphisms, especially Fok1, with the development of nutritional rickets." (PMID 36619587, 2022). "Studies in VDR null mice showed that deletion of VDR causes the loss of active calcium absorption in the proximal intestine, leading to hypocalcemia and rickets." (PMID 35779631, 2022). "Reduced VDR expression or VDR mutations are the cause of rickets and are thought to contribute to different disorders." (PMID 36246903, 2022). "Another cause of vitamin D-resistant rickets is due to vitamin D receptor mutations encoded on chromosome 12q13.11." (PMID 35299844, 2021). "Data analyses, which include a test of association between VDR gene polymorphisms and study outcomes (lymphopenia and hypovitaminosis D prevalence, mild/moderate and severe infections) will be performed using the R statistical software." (PMID 33621190, 2021). "Our results have an important translational impact, considering that hypovitaminosis D or VDR polymorphisms have been found in glaucoma patients." (PMID 34530842, 2021). "The present study investigated the distribution of the VDR gene TaqI polymorphism in older women with hypovitaminosis D (case group) compared to those with vitamin D sufficiency (control group)." (PMID 33029399, 2020). "The abnormal structure of the growth plates is one of the major clinical, radiological, and histological hallmarks of rickets observed in humans and mice with vitamin D deficiency or inactivation of the VDR or 1α-hydroxylase (CYP27B1)." (PMID 30321335, 2019).
rickets (continued). "Hereditary vitamin D-resistant rickets, also known as vitamin D-dependent rickets type 2 belongs to the second category and is caused by a mutation in VDR, rendering it unresponsive to its substrate, resulting in hypocalcaemia and early onset rickets." (PMID 29652819, 2018). "Epidemiologic and genetic studies indicate that AD is associated with hypovitaminosis D, VDR polymorphisms, and dysregulated VDR mRNA." (PMID 29318446, 2018). "Vitamin D receptor (VDR) loss results in hypocalcaemia, rickets, osteomalacia, lower cortical bone density, and increased numbers of osteoclasts." (PMID 30131710, 2018). "Our patients had near total alopecia and severe rickets findings on physical examination and X-ray findings similar to those of the two sisters carrying the same VDR mutation, previously reported." (PMID 27796266, 2017). "Mutations in the VDR gene can lead to the rickets disease, characterized by growth retardation, bone deformity among other effects and this gene was also found related to bone density in mice." (PMID 26979536, 2016). "Cumulative data indicate that functional VDR is required for hair growth, and that alopecia is unrelated to the calcium or metabolic abnormalities that cause rickets." (PMID 28377956, 2015). "Logistic regression and stratified analyses by the presence of hypovitaminosis D (≤20 ng/ml) were used to evaluate the association of the VDR variants with asthma." (PMID 26346690, 2015). "Deficiency in active 1,25-dihydroxyvitamin D (1,25(OH)2D) often associated with rickets can affect the vitamin D receptor-mediated expression of mineralization inhibitors such as DMP1." (PMID 26347868, 2015). "Multiple reports also link hypocalcemia and hypophosphatemia to bone, dentin, and enamel pathologies, including DiGeorge syndrome, vitamin D receptor (VDR)-associated rickets, and phosphate-regulating endopeptidase homolog, X-linked (PHEX)-associated rickets." (PMID 24828138, 2014). "There is also evidence in VDR mutant mice susceptible to rickets that many of the associated bone and dental (dentin and cementum) pathologies can be partially corrected via oral supplementation to correct the levels of circulating calcium and phosphate." (PMID 24828138, 2014). "Logistic regression confirmed that the GG genotype of rs10877012 (CYP27B1) was associated with hypovitaminosis D (OR = 1.8; CI: 1.1–3.0; p = 0.01), and the CT genotype of rs731236 TaqI (VDR) with RA (OR = 1.9; CI: 1.2–2.9; p < 0.01) and high DAS28-ESR (OR = 3.6; CI: 1.3–10.7; p < 0.01)." (PMID 40870018, 2025). "Nevertheless, this hypothesis is still highly supported by studies in animal models, in children with vitamin D-resistant hereditary rickets (a rare genetic disease caused by VDR mutations)." (PMID 40172435, 2025). "The first describes a child who presented with early onset rickets, hypocalcemia, secondary hyperparathyroidism, and elevated serum vitamin 1,25(OH)2D, who was found to have a heterozygous E420A variant on exon 9 of the VDR gene." (PMID 40241811, 2025). "Vitamin D-dependent rickets are caused by mutations affecting the enzymes involved in the activation or degradation of vitamin D or the action/expression of the vitamin D receptor (VDR)." (PMID 38706696, 2024). "For example, deleterious mutations in the VDR gene may cause inherited 1,25-(OH)2D3 resistant rickets, wherein mutated VDR retains the ability to bind to 1,25-(OH)2D3 but exerts an antagonistic influence on its biological outcomes." (PMID 38230221, 2024). "It is unknown exactly why the ff Fok1 VDR variant, which Is less transcriptionally active, is less common in patients with nutritional rickets." (PMID 36619587, 2022). "Although these studies suggest that VDR polymorphisms are implicated in nutritional rickets, it appears that different modifying or environmental factors can interact with these genotypes, which may explain the different behaviours in different populations." (PMID 36619587, 2022).
rickets (continued). "The remarkable effects of 25(OH)D3 administration on rickets symptoms in Vdr (R270L) rats indicate that 25(OH)D3 might be efficacious in the treatment of patients with type II rickets caused by the human VDR mutant (R274L)." (PMID 34769269, 2021). "The remarkable effects of 25(OH)D3 administration on rickets symptoms in Vdr (R270L) rats indicate that 25(OH)D3 may be efficacious in the treatment of patients with type II rickets caused by the human VDR mutant (R274L)." (PMID 32231239, 2020). "Since hypovitaminosis D has been linked to an increased frequency of asthma and otherallergic diseases, the vitamin D receptor may be involved in the mechanism of thedisease." (PMID 30066819, 2018). "They found that vitamin D receptor genotypes may predispose to rickets by increased frequency of the F allele." (PMID 27476528, 2016). "Several studies also examined the association between VDR and rickets in Chinese subjects." (PMID 24073854, 2013). "However, only a few studies have examined the association between the vitamin D receptor (VDR) and rickets." (PMID 24073854, 2013). "VDR B allele also predisposes to VDD since Egyptian B homozygotes had severe rickets." (PMID 22536488, 2012). "We therefore investigated the VDR polymorphism among Mongolian children and examined the hypothesis that the VDR polymorphism is associated with high prevalence of rickets in Mongolia and with bone properties in childhood." (PMID 17202743, 2007). "We therefore investigated whether VDR polymorphism is related to high prevalence of rickets in Mongolia and to bone properties in childhood." (PMID 17202743, 2007). "Thus, AH-1 could be a powerful agent for alternative therapeutic agent for rickets patients with VDR(R274L) mutation, as supraphysiological doses of current vitamin D-dependent therapeutic approaches such as 1,25(OH)2D3 treatment, have limited success." (PMID 35869242, 2022). "Our results suggested that some patients with vitamin D-deficient rickets may have a VDR mutation." (PMID 28377956, 2015). "These cells express the VDR gene, and mice that lack this gene develop severe rickets and osteomalacia." (PMID 38318147, 2024). "Nevertheless, this study shed light on the genetic modulation of a VDR gene SNP in the hypovitaminosis D phenotype in humans, and future studies will better elucidate the genetic, epigenetic, and molecular points involved." (PMID 37630755, 2023). "We have shown that the mice bearing the VDR L304H (VDRgem) exhibit rickets with a more severe phenotype than the VDR-null mice." (PMID 35955580, 2022). "Missense and nonsense mutations in VDR cause hereditary vitamin D–resistant rickets (HVDRR), a syndrome of severe rickets that appears soon after birth." (PMID 36619587, 2022). "There is evidence that polymorphisms in the gene that codes for the synthesis of Vitamin D receptor (VDR) are related to D hypovitaminosis." (PMID 38624931, 2021). "In VDR KO mice, hypocalcaemia and hypophosphataemia occurred, accompanied by skeletal changes as rickets and osteomalacia." (PMID 33467106, 2021). "It was found in the systemic VDR knockdown model that, the phosphate and calcium-rich diet supplemented with lactose prevented osteomalacia and rickets, thus enhancing calcium uptake by the intestine." (PMID 34899951, 2021). "The knocking out of vitamin D receptor and hypovitaminosis D can impair insulin secretion, and treatment of vitamin D can induce insulin-dependent glucose uptake." (PMID 34959910, 2021). "Seven of the amelogenesis imperfecta-associated genes (CYP27B1, EPNN1, PHEX, SLC4A1, SLC4A4, VDR, and WDR72) are known to cause rickets when mutated." (PMID 33672174, 2021). "HIV-AIDS patients typically have hypovitaminosis D. Vitamin D is a key mediator in inflammatory and infectious diseases, which VDR mediates its biological effect." (PMID 33664952, 2021). "Vitamin D-deficient/insufficient animals and humans, as well as global VDR-KO mice, exhibit hypocalcemia and rickets/osteomalacia." (PMID 32987399, 2020).